TLR7 (toll like receptor 7)
Diseases named in the same sentence as TLR7 in open-access papers (continued):
Sharing a sentence is not in itself a finding about the gene and the disease.
infection (continued). "Expression of TLR7 was not significantly altered, regardless of the condition of infection." (PMID 34358174, 2021). "Subsequent work found that TLR7 promotes a rapid wave of IL-10 secretion from CD4 T cells that inhibits early FV replication as well as a non-neutralizing IgM response within days of infection." (PMID 33202596, 2020). "Moreover, the simultaneous absence of TLR7, TLR9, and TLR13 was associated with extreme susceptibility to infection, due to the inability of resident macrophages to produce chemokines and recruit neutrophils to infection sites." (PMID 32209688, 2020). "Here, we evaluated therapeutic Ad48-SIV prime, MVA-SIV boost immunization in combination with the TLR-7 agonist GS-986 in rhesus macaque (RM) infants orally infected with SIVmac251 at 4 weeks of age and treated with a triple ART regimen beginning 4 weeks after infection." (PMID 33104758, 2020). "Given the criteria above and the fact that YY1 could target TLR7 and TLR9 signaling, type I and II interferon production/pathways, reported as effective for virus clearance during infection, if activated, establishes YY1 as the best TF with the best potential as a drug target for BCoV therapy." (PMID 32872640, 2020). "One as-of-yet unsolved aspect of the role of TLR3, TLR7, or TLR9 in detecting retroviruses is that their ligand-binding domains are located within endosomes or on the cell surface, yet release of viral RNA and reverse transcription occurs within the cytoplasm upon infection." (PMID 32751803, 2020). "Inhibition of CXCR4 activity by a single s.c. injection of AMD3100 (100 μg/foot skin), a selective CXCR4 antagonist, administered 2 h prior to infection failed to alter viral loads in the pLN of Wt and TLR7−/− mice as compared to vehicle treated littermate controls." (PMID 30930901, 2019). "Comparison of IFN-α levels in the supernatants of VSV-infected Wt and TLR7−/− BM-derived cell types at 6 and 18 h p.i. revealed that Wt and TLR7−/− pDC with strong VSV-luciferase expression at 6 h p.i. both failed to produce detectable IFN-α at this time point of infection (data not shown)." (PMID 30930901, 2019). "However, the absence of TNFα, TNFβ, and MIP-1β production suggests that MOPV- and LASV-infection did not lead to the complete activation of pDCs, in contrast to that induced by the TLR7 and TLR8 ligand R848." (PMID 30901952, 2019). "At this infection stage, ALV-J may be recognized by TLR1, TLR7 and TLR15." (PMID 30841905, 2019). "In conclusion, this study indicated that S. japonicum infection could induce TLR7 expression in both CD4+ and CD8+ T cells of the MLN in C57BL/6 mice, and importantly, the alteration of TLR7 mediates T cell response in the early phase of infection." (PMID 31930147, 2019). "Similarly, the percentage of SD-PJEC cells expressing TLR-7 was also lowered after infection with MN08, but not by IA07." (PMID 29880757, 2018). "In the present study we were not able to test for associations between TLR7 or TLR9 and susceptibility to infection due to low variability at these loci, thus we were able to analyse the selection pattern acting on these loci only based on the results of neutrality tests." (PMID 29849060, 2018). "However, the inhibition of TLR7 expression levels and higher expression of type I (IFN-α and IFN-β) IFNs were observed in chicken macrophages when treated with virulent strain NA-1 during the later stage of infection (from 48 to 72 hpi)." (PMID 29670609, 2018). "Importantly, on day 3 post infection, there was a clear and significant increase in the frequency of IFN-γ producing NK cells in the lungs of WT but not in TLR7-deficient mice compared to uninfected controls." (PMID 29497422, 2018). "In addition, a recent study conducted by Nazmi and co-workers reported increased survival in mice treated with a TLR7 agonist compared with wild-type mice due to the use of lethal dose of JEV (GP78 strain, 3 × 105 pfu/mouse) through subcutaneous route to induce infection." (PMID 28265274, 2017).
infection (continued). "In the absence of TLR7 in T cells, infection with FV induced significantly less IgG2a production." (PMID 27880772, 2016). "However Cl13 infected TLR7-/- mice primed with ArmΔGPC have undetectable viral titers after two weeks of infection suggesting that the IFN responsible for clearance was not generated though TLR7 stimulation." (PMID 25569216, 2015). "Real-time quantitative polymerase chain reaction showed that the expression of TLR3, TLR7, RIG-I, MDA5, IL-1β, IL-2, IL-6, IL-8, IFN-alpha, IFN-beta, IFN-gamma in the lungs was significantly greater than in the respective thymus genes during the early post infection stage." (PMID 26635752, 2015). "Infection of peripheral blood mononuclear cells (PBMC) from four breeds of goats and water buffalo resulted in differential viral replication kinetics and inflammatory cytokine profile including IFNα, IFNγ and TNFα with differential activation of TLR3 and TLR7." (PMID 25369126, 2014). "A recent report using an antagonist of TLR7/9 that blocks IFN-α production by plasmacytoid dendritic cells (pDCs) in SIV infected rhesus macaques had shown that pDCs are not the only source of IFN-α production in this infection model." (PMID 24603698, 2014). "However, the proportion of lymph node pDC that was BrdU+ increased significantly at day 14 post infection in both groups, reflecting the influx of recently divided pDC to lymph nodes that occurred regardless of TLR7 and TLR9 blockade." (PMID 23935491, 2013). "In contrast to IFN-α, massive numbers of TNF-α-producing cells were present in lymph nodes at both day 14 and 56 post infection, regardless of TLR7 and TLR9 blockade, with 25 to 30% of all cells in the paracortex and parafollicular cortex expressing this cytokine." (PMID 23935491, 2013). "Furthermore, upon infection, HPV further down-regulate TLR7 and 9 levels which may favor viral persistence." (PMID 22513098, 2012). "However, the differential antibody repertoire induced by TLR7 and TLR9 agonists may have a profound effect on an individual's response to infection and long-term immunity." (PMID 18652679, 2008). "Furthermore, the IL5 response to infection in male mice was not TLR7-dependent." (PMID 40143355, 2025). "In addition, to identify whether or not TLR7 was involved in RABV infection, BV-2 cells were pre-treated with or without a TLR7 inhibitor (HY-124603) for 2 h with the infection of CVS-11." (PMID 39273091, 2024). "Additionally, three individuals of P. nobilis carrying the original full‐length TLR‐7 of P. rudis appeared as naturally resistant as the hybrids and P. rudis (i.e. no infection detected), suggesting that TLR‐7 was indeed probably involved in disease resistance." (PMID 37546570, 2023). "However, we found that the differences in the percentage of CD11b+Ly6G+Ly6C−/low PMN-MDSCs or CD11b+Ly6G−Ly6Chigh M-MDSCs between WT and TLR7-KO mouse lung were not obvious after infection, which indicated that TLR7 knockout did not affect the subsets of S. japonicum infection-induced lung MDSCs." (PMID 36279265, 2022). "This is important since increased responses by mutant DCs to TLR7 stimulation, for which the natural ligand is IAV ssRNA6, would imply that IFN-β mediated anti-IAV responses may potentially play a relevant mechanistic role in facilitating IAV clearance during active infection in the mutant." (PMID 35354833, 2022). "Interestingly, the results indicated that TLR7-KO could decrease the percentage of MDSCs in the absence of infection (p < 0.05), but could dramatically increase the percentage of MDSCs infected with S. japonicum." (PMID 36279265, 2022). "Infection at delivery, but not earlier in pregnancy, was associated with significantly higher TLR3-mediated IL-6 and IL-10 responses in the first 3 months of life, and with significantly higher TLR3-/TLR7/8-/TLR9-mediated TNF-α and TLR9-mediated IL-10 responses at 6 or 12 months of age." (PMID 26580401, 2015).
infection (continued). "In addition, we found abrogation – or almost complete suppression – of infection by pseudoviruses containing the BaL or BR envelope glycoproteins in MDMs stimulated through TLR3 or TLR4, with only partial reduction observed in cells stimulated through TLR2, TLR7 or TLR9." (PMID 23028330, 2012). "However, infection of pDCs from TLR7−/− or MyD88−/− mice resulted in no cytokine production." (PMID 20661430, 2010). "Our results from the present study indicated that, during the acute phase of infection, intermediate (CD14+CD16+) and non-classical (CD14+CD16++) monocytes exhibited increased TLR7 expression." (PMID 41012652, 2025). "These analyses demonstrate that TLR7 is predominantly expressed in immune cells within both the URT and LRT, with macrophages constituting the most frequent cell type in the absence of infection." (PMID 40442368, 2025). "Regarding the Y strain infections, independently of the presence/absence of SLAMF1, there are five GO terms shared, like the positive regulation of TLR7 and TLR9 signaling pathways and the alpha–beta T cell activation." (PMID 39000601, 2024). "Gene expression analysis of the nasal tissue revealed that early infection (4 dpi) did not alter TLR expression, including that of TLR7 despite virus being present and evoking elevated IRF-7 and IFN-β expression." (PMID 37795093, 2023). "Upon the infection of RSV (strain A2) in primary human lung epithelial cells, the knocking down of TLR4, but not TLR3, TLR7, TLR8, or RIG-I results in a reduced expression of pro-IL-1β and IL-1β." (PMID 35308390, 2022). "iNOS induction in WT, TLR7-/-, TLR9-/-, and TRIF-/- Hoxb8 neutrophils after infection with A. phagocytophilum was not significantly different." (PMID 33747981, 2021). "We observed that co-culturing of leukocytes from Tlr7-/- mice, but not wildtype (WT) mice, resulted in the expression of ERV envelope protein in DFJ8 cells, indicating that there was productive infection of DFJ8 cells by infectious ERVs." (PMID 35058919, 2021). "Interestingly, the gene expressions of certain signal proteins, such as TLR7, MyD88, MDA5, MHCII, and Fc receptor, decreased in HD11 cells and PBMCs-Mφ at 12 hpi, respectively, indicating that IBV could inhibit the immune regulatory function of macrophages at the early stage of its infection." (PMID 33509253, 2021). "The variant was a cis-eQTL for IFNB1 after activation of the TLR1/TLR2, TLR4, and TLR7/TLR8 pathways, but not after infection with an influenza virus." (PMID 33147208, 2020). "In MK1-OSU cells, MN08 and IA07 significantly reduced the expressions of TLR-7 and MDA5 24 h post-infection compared to control non-infected cells." (PMID 29880757, 2018). "The induction of lung NK cell CD69 expression was, however, not fully TLR7-dependent, as significant CD69 expression was also detected in TLR7ko NK cells by day 4 post infection." (PMID 29497422, 2018). "Unlike the expression level of TLR3 and TLR7, S1PR1 expression in the tested tissues after infection with ZH283 was lower than that in response to infection with SW8." (PMID 28676793, 2017). "There was no significant change in pDC HLA-DR, CD86 or CD123 expression, either without stimulation (NIL) or following TLR7 or TLR9 stimulation, when baseline was compared to peak-infection in eight individuals." (PMID 28572564, 2017). "It is not likely that the knockdown of TLR7/8 impaired HCV entry, as their simultaneous knockdown increased HCV RNA levels in cells at 24 hours post-infection." (PMID 26023919, 2015). "For example, HIV-mediated inflammasome activation is similarly independent of productive infection and dependent on endocytic uptake of viruses, leading to activation of the inflammasome in monocytes via TLR8 (another ssRNA sensor) and not TLR7." (PMID 26295405, 2015). "In macaques that were SIV-infected without concurrent TLR7 and TLR9 blockade we detected a robust and transient increase in plasma levels of IFN-α which peaked at day 11 post infection." (PMID 23935491, 2013).
infection (continued). "Similar to IFN-α response following TLR7 stimulation, the production of IL10 in response to TLR3, 7, 8 ligands or following infection with PR8 was not dependent on “in vivo” stimulation by sex hormones and/or Cortisol." (PMID 22768144, 2012). "Interestingly, despite their enhanced responsiveness to the viral RNA, TLR7- and TLR8-overexpressing cells did not react to the infection with replication-competent SARS-CoV-2, since we measured only negligible eGFP expression by flow cytometry." (PMID 39963132, 2025). "In addition, it showed a dramatic increase of TLR7 in macrophages and B220+ cells by mucosal MNV infection compared with non-mucosal infection." (PMID 39939342, 2025). "Consistent with the prior result, Tlr7−/y pDC in infected chimeras exhibited long tracks and did not arrest while WT pDC had much shorter tracks and arrested, establishing that TLR7 signaling intrinsic to pDC, is required for them to stop during infection." (PMID 36278864, 2022). "In addition to LPS, the rs12553564 variant was found to be an eQTL for IFNB1 in monocytes activated by Pam3CSK4 (targeting the TLR1/TLR2 receptors) and R848 (targeting the TLR7/TLR8 receptors), but not after infection with an influenza virus." (PMID 33147208, 2020). "However, our results indicated that USP19-deficiency did not affect induction of downstream effector genes after infection with both RNA and DNA viruses or stimulation with TLR2 and TLR7/8 ligands in mouse primary immune cells." (PMID 31511519, 2019). "The signal to mediate this increase was likely independent of IAV recognition by TLR7, or by IAV-induced release of CpG rich mitochondrial (mt)DNA as TLR7 and TLR9 agonist stimulation lead to downregulation of TLR9 gene expression relative to mock infection." (PMID 30682165, 2019). "In the absence of infection, endogenous IL-6 protein was barely detected in the cerebral cortex of WT or TLR7-/- mice, whereas upon EV71 infection IL-6 levels were significantly elevated in the cerebral cortex of WT mice relative to TLR7-/- mice." (PMID 31730654, 2019). "Interestingly, direct infection of isolated alveolar macrophages with PR8 also shows an increase in TLR9, TLR7 and TLR3, with no changes in TLR2, and reduced TLR4." (PMID 30682165, 2019). "At peak-infection, more pDC produced IFN-α in response to TLR7 (p = 0.02) or TLR9 stimulation (p = 0.08), when compared to baseline hence, the ability of pDC to produce IFN-α was not diminished during early P. falciparum blood-stage infection." (PMID 28572564, 2017). "Further examination of the endosomal TLR pathway using ODN 2088, an antagonist of the endosomal TLR7/8/9 pathways, implied that while TLR7 and TLR9 were each upregulated versus mock infection with either UV-inactivated or live RSV neither played a role in the IFN-β or IDO expression we observed." (PMID 27695127, 2016). "Although it is well known that influenza virus activates both TLR3 and TLR7 pathways, either activation of TLR3 or TRL7 alone could not elucidate the IFN-mediated antiviral defense during infection." (PMID 26206138, 2015). "To that end, we stimulated different TLRs with their known ligands (e.g. TLR2 was stimulated with Pam3Csk4; TLR4 was stimulated with LPS, TLR7 was stimulated with imiquimod and TLR9 was stimulated with CpG-DNA) in the presence or absence of stimulation with Rv2463 or infection with M. tb H37Rv." (PMID 25915405, 2015). "TLR7 and TLR3 were both activated upon LV infection, but not upon Lena infection." (PMID 24643046, 2014). "Infection of human or murine pDCs with live WT VAC also fails to induce type I IFN production, whereas infection with heat-inactivated vaccinia (Heat-VAC, by incubating at 55°C for 1 h) induces TLR7/MyD88-dependent type I IFN production." (PMID 24743339, 2014). "TLR3 and TLR7 are also involved in sensing CMV infection, although it is not clear whether they are activated during initial infection or later during the replication cycle." (PMID 22319449, 2012).
infection (continued). "TLR3 and TLR7 are down-regulated and NOD2, RIG-1 and MDA-5 do not appear to be stimulated in chronic KD, though they may be transiently activated during the precipitating infection(s)." (PMID 36769320, 2023).